NOTCH3 (notch receptor 3)
Diseases named in the same sentence as NOTCH3 in open-access papers (continued):
Sharing a sentence is not in itself a finding about the gene and the disease.
breast carcinoma (continued). "Collectively, ectopic overexpression of Notch3 forces alteration of LLGL2 subcellular positions, which may lead to a failure of directional migration of breast cancer cells." (PMID 31096822, 2019). "We used MDA-MB-231-N3ICD cells to investigate the function of the Notch3/GATA-3 axis in distant spreading of breast cancer, with/without GATA-3 knockdown, in tumor xenograft models." (PMID 30100605, 2018). "Forced expression of the mitotic Aurora kinase A (AURKA), which promotes breast cancer metastases, failed to restore the invasive capacity of NOTCH3-null cells, demonstrating that NOTCH3 expression is required for an invasive phenotype." (PMID 30180881, 2018). "Furthermore, we also provided evidence for a pivotal role of Notch3 in the suppression of EMT and metastasis via trans-activating ERα in breast cancers." (PMID 30109262, 2018). "We therefore determined expression of Notch3 and GATA-3 in tissue samples from breast cancer patients with immunohistochemistry (IHC) and explored their possible relationship with progesterone receptor (PR) and ER statuses, as well as their associations with other clinicopathologic features." (PMID 30100605, 2018). "Our findings expand our current knowledge on Notch3 and GATA-3's roles in breast cancer metastasis." (PMID 30100605, 2018). "Notch3 and GATA binding protein 3 (GATA-3) have been, individually, shown to maintain luminal phenotype and inhibit epithelial–mesenchymal transition (EMT) in breast cancers." (PMID 30100605, 2018). "Intriguingly, two recently published articles of our studies demonstrated that Notch3, but not other Notch receptors, is positively correlated to ERα both in breast cancer cells and breast carcinoma tissues." (PMID 30100605, 2018). "More recent studies showed that leptin induced expressions of Notch1, 3, 4 in breast cancer cells, and inhibition of leptin signaling, led to decreased protein expression levels of NICD1, NICD4, Notch3, JAG1 and survivin as well as reduced mRNA levels of Notch receptors, ligands and targets." (PMID 27185268, 2016). "As our prior experiments established an inverse correlation between Notch3 expression and EMT, we sought to determine whether Notch3 can in fact inhibit EMT in breast cancer epithelium." (PMID 27841855, 2016). "Here we focused on the phosphorylation of Notch1, as expression of Notch 3 was restricted to MCF-7 breast cancer cells and not present in PC-3 prostate cancer cells, and the exact role of Notch3 in tumor progression is still under debate." (PMID 27281612, 2016). "For example, IL-6/Notch-3 signaling increases CAIX expression and stimulates breast cancer cell invasion and HER2+ and triple negative breast cancers which express CAIX are associated with poor prognosis and high levels of early metastases to bone, lung and brain." (PMID 26259239, 2015). "γ-secretase inhibitor (GSI) treatment inhibited the binding of NOTCH3/MAML1 complex to HES1 promoter, indicating that Notch pathway is active in these breast cancer cells and MAML1 might be a co-activator of Notch signaling in breast cancer." (PMID 20010940, 2010). "Furthermore, a recent clinical study reported that the expression level of Notch1, Notch3, and JAG-1, one of the Notch ligands, were inversely correlated with the overall clinical outcomes in breast cancer patients." (PMID 19660128, 2009). "NOTCH3 may inhibit the progress of breast cancer through a multi-layer system, and it may at least partially inhibit the expression of ZEB1 and inhibit the proliferation, migration and EMT in breast cancer cells by inducing miR-223." (PMID 38164285, 2024). "Interestingly, in mouse mammary glands, Notch3 is expressed by luminal progenitor cells, described as the cell of origin of luminal, HER2 and basal breast cancers, and inhibits their proliferation, suggesting that it may have a tumor suppressive activity." (PMID 36854682, 2023).
breast carcinoma (continued). "Notably, high mRNA expression of both Notch3 and GSK3β predicted greater relapse-free survival in overall (p = 1.8 × 10−5) and luminal A breast cancer patients (p = 0.0082), but not luminal B, basal-like or Her 2 subtypes." (PMID 36139447, 2022). "In addition, Notch3 and PTEN overexpression in breast cancer patients indicated a better prognosis." (PMID 34006834, 2021). "In order to evaluate the oncogenic potential of NOTCH1 and NOTCH3 on breast cancer growth in vivo, we used the CRISPR-/Cas9-based genomic editing to prepare MCF-7 breast cancer cell-based KO cell lines lacking endogenous expression of either NOTCH1 or NOTCH3 genes and the corresponding proteins." (PMID 33775697, 2021). "Therefore, the current finding predicted miR-488 as a tumor suppressor molecule in breast cancer, and demonstrated that Notch3/miR-488/FSCN1 axis is established and involved in regulating the metastasis of breast cancers, providing novel therapeutic targets for patients with breast cancers." (PMID 33099573, 2020). "Taken together, Notch3 may participate in inhibiting EMT in breast cancer by the classical or non-classical signaling pathway, and the transmembrane domain may play an important role during this process." (PMID 31096822, 2019). "Interestingly, enforced N3ICD expression results in the upregulation of GATA-3 in breast cancer cell lines with ERα-negative phenotype, while suppressing Notch3 expression downregulates GATA-3 expression in ERα-positive cells." (PMID 30100605, 2018). "Because our results indicate that NOTCH3-expressing cells originate in vMCF-7∆Raf1 xenografts, we employed the CRISPR-Cas9 gene editing technology to generate unique NOTCH3-knockout breast cancer cells (vMCF-7Raf-1 1GXCRISPR-NOTCH3) and assessed their stemness and invasive properties." (PMID 30180881, 2018). "In vivo leptin signaling inhibition reduced Notch and target expression (NICD1, NICD4, Notch3, JAG1 and survivin), suggesting that leptin-Notch crosstalk could be involved in the reported higher incidence, aggressiveness and poor prognosis of breast cancer in obese patients." (PMID 30004402, 2018). "Moreover, in breast cancer epithelial cells, Kibra might be a point of convergence in the Hippo/YAP signaling pathway as activated by Notch3 to have a pivotal role in inhibiting EMT." (PMID 27841855, 2016). "Moreover, IL-6 autocrine loop could trigger a Notch-3/Jagged-1 pathway to enhance the growth and aggressive phenotypes of mammospheres derived from malignant mammary tissue or MCF7 breast cancer cell line." (PMID 22023707, 2011). "However, the molecular mechanism of Notch3 in breast cancer has not yet been completely deciphered." (PMID 38124049, 2023). "Our results highlight a novel mechanism for exploring how Notch3 regulates EMT as well as the crosstalk between Notch and Wnt signaling pathways; this may have important implications for identifying new biomarkers for the prognosis of and as therapeutic targets in breast cancer." (PMID 36139447, 2022). "NOTCH3 expression did not significantly correlate with the prognosis of patients with lung cancer (PPS HR = 1.19, 95% CI = 0.92–1.54, P = 0.18) or breast cancer (OS HR = 0.85, 95% CI = 0.61–2.03, P = 0.098; PPS HR = 1.2, 95% CI = 0.95–1.51, P = 0.13)." (PMID 38906903, 2024). "TCGA breast cancer dataset (BRCA) analysis confirmed a weak but significant negative correlation between Notch3 expression and Notch3 methylation in the first CpG island that includes the promoter, the first exon and part on the first intron." (PMID 36854682, 2023). "We observed a negative correlation between Notch3 methylation and Notch3 expression using the GSE44837 and GSE44826 dataset containing data on mRNA expression and methylation in the same breast cancer cell lines." (PMID 36854682, 2023). "NOTCH3 was also found to be upregulated in CD44+ populations of normal cells and breast cancer cells." (PMID 24355041, 2013).
breast carcinoma (continued). "However, the relationship and potential regulatory mechanism between Notch3 and STAT5A was not verified in HER2-positive subtype of breast cancer." (PMID 38124049, 2023). "However, the mechanism of the interaction between Notch3 and PTEN has not been extensively studied in breast cancer." (PMID 34006834, 2021).
Cerebral autosomal dominant arteriopathy with subcortical infarcts and leukoencephalopathy (117 papers, 2009 to 2026). "Notch3 mutations cause CADASIL (Cerebral Autosomal Dominant Arteriopathy with Subcortical Infarcts and Leukoencephalopathy), a hereditary autosomal dominant disease, characterized by progressive degeneration of smooth muscle cells of small brain vessels, leading to dementia and death." (PMID 35611804, 2022). "CADASIL (Cerebral Autosomal Dominant Arteriopathy with Subcortical Infarcts and Leukoencephalopathy) is a small vessel disease caused by mutations in NOTCH3 that lead to an odd number of cysteines in the epidermal growth factor (EGF)-like repeat domain, causing protein misfolding and aggregation." (PMID 34298974, 2021). "Cerebral autosomal dominant arteriopathy with subcortical infarcts and leukoencephalopathy (CADASI) is an autosomal dominant disease caused by rare mutations of the gene encoding the neurogenic locus notch homolog protein 3 (NOTCH 3 gene) located on chromosome 19p13." (PMID 28283957, 2017). "CADASIL (Cerebral Autosomal Dominant Arteriopathy with Subcortical Infarcts and Leukoencephalopathy) is a hereditary small vessel disease caused by mutations in the NOTCH3 gene, leading to toxic NOTCH3 protein accumulation in the small- to medium sized arterioles." (PMID 26715087, 2015). "It has been shown that Notch3-null mice is defected in the vascular development, and Notch3 mutations are responsible for heritable cerebral autosomal dominant arteriopathy with subcortical infarcts and leukoencephalopathy (CADASIL) syndrome with alterations in vascular smooth muscle cells (VSMCs)." (PMID 26380809, 2015).
ovarian carcinoma (103 papers, 2009 to 2026). A malignant neoplasm originating from the surface ovarian epithelium. "Here, we investigated the effects of 27 kDa, 183 kDa and 1000 kDa HA on ES-2 ovarian cancer cells overexpressing the stem cell associated protein, Notch3." (PMID 37815603, 2023). "Overexpression of Notch3 is associated with ovarian cancer recurrence and chemoresistance to carboplatin, which predicts a poor prognosis in ovarian cancer." (PMID 34277625, 2021). "Overexpression, gene amplification, and abnormal activation of NOTCH3 are associated with different cancers including ovarian cancer." (PMID 33316986, 2020). "While in healthy ovarian tissue samples the Notch pathway is inactive, HGS ovarian cancer is associated with an active Notch pathway and activating NOTCH3 gene mutations or amplifications in about two third of the patients." (PMID 33120947, 2020). "Activation of Notch3 has been associated with ovarian cancer cells adhesion to peritoneal cells and cancer cell metastatic outgrowth." (PMID 33198378, 2020). "Overexpression, gene amplification and mis-activation of Notch3 are associated with different cancers, in particular triple negative breast cancer and ovarian cancer." (PMID 32210034, 2020). "Notch3 gene amplification resulting in significant protein overexpression has been linked with proliferation and survival of ovarian carcinomas as inactivation of Notch3 suppressed proliferation and promoted apoptosis in cell lines overexpressing Notch3." (PMID 32211044, 2020). "We propose that Notch3 activation in ovarian cancer cells causes increased adherence to collagen-rich peritoneal surfaces." (PMID 32525899, 2020). "Within all four Notch receptors, Notch3 is amplified in ovarian cancer and associated with its progression." (PMID 31182109, 2019). "Notch3 has been shown to be associated with cancer stem cells (CSC) in ovarian cancer, where its expression correlates with bad prognosis." (PMID 30555629, 2018). "Notch 3 mRNA high expression was also associated with favorite OS in clinical stage III ovarian cancer patients, HR 0.83 (0.7–0.99), p = 0.037." (PMID 28415574, 2017). "Overexpression of Notch3 is associated with chemoresistance and poor overall survival of human ovarian cancer patients and induced resistance to carboplatin in ovarian cancer cells." (PMID 28416766, 2017). "Notch 3 protein overexpression was associated with ovarian cancer metastasis, chemoresistance and poor overall survival in ovarian serous cancer patients." (PMID 28415574, 2017). "While many authors reported that Notch3 plays a role in ovarian cancer cell proliferation, tumor growth, and metastasis, additional investigations revealed that Notch3 signaling is implicated in chemoresistance." (PMID 29069826, 2017). "Recent studies have indicated an association between NOTCH1 or NOTCH3 and cisplatin resistance in squamous head and neck and ovarian carcinomas and in EBV-associated naso-pharynx carcinomas, respectively." (PMID 25954607, 2015). "Expression of neurogenic locus notch homolog 3 (Notch3) is associated with chemoresistance and poor overall survival in ovarian cancer patients." (PMID 25010594, 2014). "Previous studies by our group and others have shown that Notch3 upregulation is related to the recurrence of ovarian cancer and is associated with a poor prognosis." (PMID 25356737, 2014). "Similarly, using the combinational approach in ovarian cancer, the NOTCH3 gene was knocked down, which encoded a marker involved in ovarian cancer recurrence and chemotherapy resistance." (PMID 40860190, 2025). "Similarly, Notch3 gene amplification and expression are associated with ovarian cancer and Notch3 signalling has been shown to promote breast and ovarian tumour cell growth, survival and metastasis." (PMID 32210034, 2020). "Notch3 expression is known to be amplified in ovarian cancer and associated with its progression." (PMID 33198378, 2020).
ovarian carcinoma (continued). "In T-all cells miR-150, normally highly expressed in the lymphoid lineage, is reduced in expression and this loss may therefore contribute to increased Notch3 levels as has also been found in lung adenocarcinona and ovarian cancer." (PMID 32210034, 2020). "Many groups have linked Notch3 expression to clinical prognosis in advanced ovarian cancer." (PMID 31182109, 2019). "In the present study, we observed that miR-150 directly targets Notch3, an oncogene related with drug resistance in ovarian cancer, and that patients with HGSC were significantly associated with downregulation of miR-150, supporting that miR-150 is a tumor supperssor." (PMID 29069826, 2017). "Furthermore, several groups have linked Notch3 expression to the clinical prognosis of ovarian cancer." (PMID 25366565, 2014). "We recently investigated the effects of different molecular weight HA in an ovarian cancer stem cell model by over‐expressing Notch3 intra‐cellular domain (NICD3) in ES‐2 cells." (PMID 40356021, 2025). "Proteomics analysis was performed to identify novel proteins regulated by different molecular weight HA (27, 183 and 1000 kDa) in ES‐2 ovarian cancer cells over‐expressing Notch3 intra‐cellular domain." (PMID 40356021, 2025). "This mechanistic insight aligns with previous studies where NOTCH3 silencing attenuated malignant phenotypes in bladder and ovarian cancers by restricting proliferation and inducing apoptosis." (PMID 41090505, 2025). "The aptamer successfully targeted VEGF signaling in cisplatin-resistant cells via a nanoparticle chimera delivery system, which effectively knocked down the NOTCH3 gene for tumor regression in ovarian cancer." (PMID 40860190, 2025). "Its oncogenic activity has been reported in stage IA lung adenocarcinoma and ovarian cancer by Notch3 targeting." (PMID 38741808, 2024). "These compelling observations show that COMP selectively activates the Notch3 signaling pathway in ovarian cancer cells." (PMID 38615020, 2024). "The results revealed a higher number of spots per cell in COMP-treated ovarian cancer cells compared to the control group, indicating an increased interaction of Notch3 and Jagged1 in the presence of COMP." (PMID 38615020, 2024). "Notch3 appears to be particularly important in ovarian cancer, as it has the greatest increase in Notch3 expression compared to every cancer in the TCGA database." (PMID 39802952, 2024). "In ovarian cancer, Nr2f6 promotes cell proliferation by tethering the histone acetylase P300 to the Notch3 promoter." (PMID 38682559, 2024). "IL-8 binding to CXCR1/2 also promotes CSC development and cisplatin resistance in ovarian cancer by activating Notch3." (PMID 39802952, 2024). "In this study, we overexpressed NICD3 in an ovarian cancer cell line with low NOTCH3 expression (ES-2) to simulate a stem-like model." (PMID 37815603, 2023). "Another ovarian cancer study demonstrated that side population cells with enhanced CSC features had high Notch3 expression and inhibition of Notch signaling increased response to chemotherapy and reduced tumor burden in vivo." (PMID 37815603, 2023). "Ovarian cancer cells express Notch1, Notch2, Notch3, Notch4 and Jagged2, while ECs located in the ovary express Jagged1 and Dll1 and Dll4 ligands." (PMID 36430649, 2022). "PBX1 is the direct downstream target gene of the NOTCH3 signaling pathway, which is necessary for ovarian cancer cell survival and proliferation." (PMID 35041720, 2022). "In ovarian cancer, NOTCH3 overexpression induces EMT, chemoresistance, and is associated with poor overall survival." (PMID 35073251, 2022). "By targeting Notch3, MiR-136 inhibits ovarian cancer stem cell activity and increases PTX antitumor efficacy in ovarian cancer cells." (PMID 36439901, 2022).